TRIB2 (tribbles pseudokinase 2)
Diseases named in the same sentence as TRIB2 in open-access papers (continued):
Sharing a sentence is not in itself a finding about the gene and the disease.
lung carcinoma (continued). "TRIB2 expression has been shown to be elevated in lung cancer, and has been found to induce apoptosis through downregulation of the transcription factor CCAAT/enhancer-binding protein alpha (C/EBPα)." (PMID 22589742, 2012). "In the last decade, investigation on the roles of TRIB2 in lung cancer found that some microRNAs like miR-511, miR-1297 and let-7c can effectively inhibit lung cancer proliferation by suppressing the expression of TRIB2 and consequently increasing that of C/EBPα." (PMID 35790734, 2022). "Our previous studies supported that TRIB2 played an oncogenic role in tumorigenesis of lung cancer." (PMID 35790734, 2022). "Following TRIB2 overexpression, the number of migrated cells increased significantly (p < 0.05), suggesting that TRIB2 promoted the migration of lung cancer cells." (PMID 34646775, 2021). "The current study further verified whether the oncogenic role of TRIB2 depends on RFWD2 in regulating lung cancer cell proliferation." (PMID 34646775, 2021). "TRIB2 was overexpressed in lung cancer tissue compared with the adjacent normal lung tissue." (PMID 34646775, 2021). "Therefore, we propose that TRIB2 may promote lung cancer cell proliferation via the following mechanisms: At first, TRIB2 binds RFWD2-E3 Ub ligase based on C-terminal RFWD2-binding motif to form a dipolymer, which increases phosphorylated RFWD2 levels." (PMID 34646775, 2021). "Data from TCGA database further supported that TRIB2 and PKM2 expression was higher in lung carcinoma tissues (p < 0.01)." (PMID 35790734, 2022). "The overexpressed PKM2 and TRIB2 increased the expression of GLUT1, LDHA, and PTBP1 to promote the aerobic glycolysis in lung cancer cells." (PMID 35790734, 2022). "Compared with that in controls, TRIB2 overexpression would promote lung cancer cell proliferation, whereas blocking PKM2 attenuated the tumorigenic role of TRIB2 in vivo." (PMID 35790734, 2022). "qRT-PCR results showed that the expression of TRIB2 and PKM2 was higher in lung carcinoma samples than that in controls (p < 0.01), and TRIB2 was positively correlated with PKM2 expression (p = 0.009)." (PMID 35790734, 2022). "The expression of TRIB2, PKM2, and p-PKM2 was higher in the lung cancer cells than that in the controls." (PMID 35790734, 2022). "Our results showed that TRIB2 can promote cancer cell proliferation and migration, interact with RFWD2, and regulate RFWD2-related gene expression in lung cancer cells." (PMID 34646775, 2021). "Moreover, compared with those in lung para-carcinoma samples, the levels of TRIB2, PKM2, and p-PKM2 were elevated in lung carcinoma samples." (PMID 35790734, 2022). "Of note, TRIB2 and PCBP2 were also important for maintaining the viability of lung cancer A549 cells via GPX4, indicating that these effects might not be restricted to liver cancer cells." (PMID 33414446, 2021). "Furthermore, siRNA- and control-treated cells were injected subcutaneously into the backs of BALB/C-nude mice to produce xenografts to investigate the effects of TRIB2 and RFWD2 on the tumorigenesis of lung cancer cells in vivo." (PMID 34646775, 2021).
leukemia (16 papers, 2013 to 2025). A malignant (clonal) hematologic disorder, involving hematopoietic stem cells and characterized by the presence of primitive or atypical myeloid or lymphoid cells in the bone marrow and the blood. "TRIB2 re-expression or pharmacological activation of p38 MAPK signalling in TRIB2 deficient leukemia cells sensitized the cells to chemotherapy-induced apoptosis." (PMID 34070799, 2021). "Trib2 deficient leukaemia cells had impaired MAPK stress responses, evaded cell cycle checkpoint control mechanisms, and resisted chemotherapy-induced apoptosis." (PMID 29670085, 2018). "Further studies have associated high and low levels of TRIB2 with leukaemia subtypes with distinct genetic backgrounds." (PMID 29670085, 2018). "Here, we demonstrated that Trib2 deficiency conferred a growth and survival advantage both at steady state and in stress conditions in leukaemia cells." (PMID 29670085, 2018). "Here we used the oncofusion gene NUP98/HOXA9 (NH9) as a deregulated HOX myeloid leukaemia model to investigate the effects of Trib2 deficiency in leukaemia cells." (PMID 29670085, 2018). "p38 is a regulator of key cell cycle regulators (p21, p16, p19, GADD45), signalling molecules (Chk1, γH2Ax), TFs (Egr1, Fos and Jun) which are inappropriately activated in Trib2 deficient leukaemia cells." (PMID 29670085, 2018). "Among them, CTDSPL and TRIB2 are closely associated with leukemia cell apoptosis and were chosen to be further validated in HEK-293 T cells using luciferase reporter assays." (PMID 24191888, 2013). "In contrast, Trib2 deficient leukaemia cells continued to enter mitosis and survive." (PMID 29670085, 2018). "Trib2 re-expression or pharmacological activation of p38 in Trib2 deficient leukaemia cells sensitised the cells to chemotherapy-induced apoptosis comparable with wild type leukaemia cells." (PMID 29670085, 2018). "We showed that Trib2 deficient leukaemia cells had defective MAPK p38 signalling, which associated with a reduced γ-H2Ax and Chk1 stress signalling response, and continued proliferation following stress, associated with inefficient activation of cell cycle inhibitors p21, p16 and p19." (PMID 29670085, 2018). "Furthermore, Trib2 deficient leukaemia cells were more resistant to chemotherapy than wild type leukaemia cells, having less apoptosis and continued propagation." (PMID 29670085, 2018). "To test whether the inappropriate stress response of Trib2 deficient leukaemia cells results in the propagation of drug-resistant myeloid leukaemia cells, we performed DNR washout (wo) experiments." (PMID 29670085, 2018). "Together these data demonstrate a role for Trib2 as a major orchestrator of cell cycle check point and stress signalling pathways in leukaemia, required for efficient activation of p38, Chk1 and γ-H2Ax, and stress-induced p21 expression." (PMID 29670085, 2018). "The leukaemias generated from Trib2 transduced GMP derived cells were all AMLs, identified as CD11b+Gr1+ cells and a lack of expression of B and T cell markers." (PMID 29599919, 2018). "Our data identify Trib2 as a central regulator of p38-mediated stress signalling pathways and leukaemia cell cycle control." (PMID 29670085, 2018). "Our study identified the granulocyte-macrophage progenitor (GMP) subpopulation as a potent leukaemia initiating cell of Trib2-driven AML in vivo." (PMID 29599919, 2018). "Despite being capable of driving myeloid leukemia when overexpressed alone, it is assumed that cooperating lesions occur in TRIB1 and TRIB2 mouse leukemia models." (PMID 27908682, 2017). "Enforced expression of Trib2 by retroviral transduction induces potent murine AML and Trib2 is a target gene of MEIS1 in HOX-induced murine leukemia." (PMID 27462446, 2016). "In contrast, all of the mice receiving Trib2-/- cells transduced with L1601PΔP developed leukemia with a median survival of 75 days." (PMID 27191957, 2016).
leukemia (continued). "Tribbles homolog 2 (Trib2) is a member of Tribbles protein pseudokinases and involves in apoptosis, autoimmunity, cancer, leukemia and erythropoiesis, however, the physiological function of Trib2 in hematopoietic system remains to be elucidated." (PMID 27550848, 2016). "The leukemic cells were capable of serial transfer; however, mice receiving sorted Trib2-/- cells expressing either ICN or L1601PΔP succumbed to leukemia more quickly than those receiving sorted Trib2+/+ cells." (PMID 27191957, 2016). "Moreover, Kim et al47 revealed that the MLL-TET1 fusion protein inhibits myeloid differentiation by up-regulating tribbles pseudokinase 2 (Trib2), a crucial factor for leukemia cell survival and differentiation arrest." (PMID 40520993, 2025). "Lastly, the interactions between TRIB2 and other T cell signaling pathways may be useful in uniquely identifying leukemia subtypes and can further advance our understanding of T‐ALL pathology." (PMID 33822486, 2021). "The knockdown of TRIB2 in leukaemia cells led to leukaemia cell death." (PMID 29670085, 2018). "This newly identified role indicates that Trib2 may counteract the propagation and chemotherapy resistance of leukaemia cells." (PMID 29670085, 2018). "It remains unclear whether the LIC in a Trib2+ leukaemia is a HSC or a more committed progenitor cell." (PMID 29599919, 2018). "However, in vivo Trib2 was only able to initiate leukaemia with potency from the GMP, with incomplete penetrance from the HSC, and not at all from the CMP and MPP." (PMID 29599919, 2018). "This suggests that the decrease in leukemia survival is not a general property of Trib2-deficient hematopoietic progenitors." (PMID 27191957, 2016). "Interestingly, high TRIB2 expression alone may adequately distinguish a T cell profile among all subtypes of leukemia and therefore, may act as potential marker for malignancies with T cell features." (PMID 33822486, 2021). "However, the ability of Trib2, and other oncogenes, to generate leukaemia from functionally and phenotypically distinct stem and progenitor populations also suggests that there are overlapping gene expression signatures initiated by different oncogenes which facilitate leukaemic transformation." (PMID 29599919, 2018). "As we have demonstrated a role for Trib2 in leukaemia cell cycle control in response to stress, we hypothesized that Trib2 is an inducible component of the cellular stress response pathways, contributing to check point activation and survival or death decision." (PMID 29670085, 2018). "TRIB2 (and TRIB1) expression promotes AML in HOX-dependent leukaemias, and in acute promyelocytic leukaemia (APL)." (PMID 29599919, 2018). "Gene expression analysis has revealed that TRIB2 expression levels, while generally low in AML, are higher in PML-RARA-positive leukemia than in PML-RARA-negative leukemia." (PMID 27908682, 2017). "This does not seem to be the case, however, as transduction of Trib2-deficient cells with the myeloid oncogene, MLL-AF9, did not decrease leukemia latency." (PMID 27191957, 2016). "TRIB2 is cyclically expressed during the cell cycle and has the ability to promote the proteasomal degradation of the mitotic regulator CDC25C, which might explain some of the uncontrolled proliferation characteristics of leukemia." (PMID 27908682, 2017). "Thus, the decreased latency observed in the Notch T-ALL model is specific to T-ALL and not a general feature of leukemia induction in retroviral models transducing Trib2-null donor cells." (PMID 27191957, 2016). "Finally, dual-luciferase reporter transfection assay and western blot analysis on clinical samples and leukemia cell lines further supported that miR-99a played a potential oncogene role by targeting CTDSPL and TRIB2 in most pediatric myeloid leukemia patients." (PMID 24191888, 2013).
leukemia (continued). "Additionally, they demonstrate that TRIB2 promotes cellular efflux functions of doxorubicin by increasing the MDR1 and MRP1 cell membrane transporters, considered as “drug resistance proteins” because they work as drug efflux pump mediating multidrug resistance of human leukemia cells." (PMID 34070799, 2021).
liver cancer (14 papers, 2016 to 2024). An epithelial or non-epithelial malignant neoplasm that arises from the liver. "TRIB2 is also specifically regulated by Wnt signaling in liver cancer cells, which is associated-Ub E3 ligase-TrCP, RFWD2, and Smurf1 reducing TCF4/β-catenin expression." (PMID 34646775, 2021). "Knockdown of TRIB2 inhibited hepatic stellate cells activation and liver fibrosis in vitro and in vivo, suggesting TRIB2 as an attractive therapeutic target for hepatic fibrosis and fibrosis-associated liver cancer." (PMID 34070799, 2021). "In a study in Bel-7402 and SMMC-7721 liver cancer cells, Yao and colleagues found that sGCα1 participated in tribbles pseudokinase 2 (TRIB2) protein-induced HBP, and O-GlcNAcylation." (PMID 39337539, 2024). "Another study reported that the dysregulation of phosphorylation and ubiquitination by p70S6K and Smurf1 led to the stability of TRIB2 and an oncogenic phenotype in liver cancer." (PMID 39199296, 2024). "Trib2 can be a target for the Wnt/β-catenin pathway downstream and regulates liver cancer cell growth and transformation." (PMID 33794905, 2021). "The effects by which βTrCP-mediated ubiquitination and followed degradation of TFRC to decline labile iron are critical for TRIB2 to desensitize liver cancer cells to ferroptosis." (PMID 34315867, 2021). "Given that TRIB2 is upregulated and pro-tumorigenic in liver cancer cells, we thereby elucidate another role of TRIB2 to boost liver tumorigenesis via sustaining liver cancer cells in a ferroptosis-resistant state." (PMID 34315867, 2021). "TRIB2 levels were generally elevated in the liver cancer cell lines (Bel-7402, Bel-7404, HepG2, SMMC-7721 and Huh7 cells) compared to HL-7702 hepatocyte line." (PMID 33414446, 2021). "Here, we demonstrated that deletion of TRIB2 sensitized ferroptosis via lifting labile iron in liver cancer cells." (PMID 34315867, 2021). "Recently, we have identified the role of TRIB2 to relieve oxidative damage in liver cancer cells via declining the availability of Ub that for the ubiquitination of GPX4." (PMID 34315867, 2021). "Recently, the roles of TRIB2 are expanded by our study demonstrating that TRIB2 can modulate proteasome function for the reduction of global Ub and protection of liver cancer cells against oxidative stress." (PMID 34315867, 2021). "Together, these data reveal the complexity of TRIB2 and ubiquitin proteasome system interactions in liver cancer cells and highlight the importance of cell context in TRIB2 protein function." (PMID 34070799, 2021). "In liver cancer, Trib2 shows high stability and interacts with βTrCP to accelerate Yes-associated protein (YAP) stabilization (Hippo pathway) and promote cancer cell proliferation." (PMID 33794905, 2021). "In the current study, we have demonstrated that TRIB2 has a novel role to desensitize liver cancer cells to ferroptosis, and a declined labile iron level is essential for such a process." (PMID 34315867, 2021). "In liver cancer, TRIB2 functions as an adaptor protein and promotes YAP protein stabilization through the E3 ubiquitin ligase βTrCP, contributing to cancer cell proliferation and transformation." (PMID 30541550, 2018). "TRIB2 was shown to integrate Wnt/β-catenin signaling in liver cancer cells, although it was suggested to act downstream of Wnt, which differs from the present results." (PMID 29176948, 2017). "Further evidence for TRIB2 as a modulator of tumorigenic activity comes from liver cancer cells, where the overexpression of TRIB2 was shown to negatively regulate WNT signaling activity, leading to inhibition of cell growth." (PMID 27908682, 2017). "TRIB2, which is involved in tumorigenesis in various cancers, was shown to increase β-catenin nuclear accumulation in liver cancer cells." (PMID 29176948, 2017).
liver cancer (continued). "In this cancer model, sGCα1 is suggested as a main component of the HBP, facilitating the activation of OGT enzyme, which catalyzes O-GlcNAcylation and activation of TRIB2, thereby contributing to the maintenance of a transformative phenotype of liver cancer cells." (PMID 39337539, 2024). "Moreover, TRIB2 regulated proteasome function to inhibit ubiquitin stability, resulting in the protection of liver cancer cells against oxidative stress." (PMID 39199296, 2024). "In addition, TRIB2 contributes to the negative regulation of WNT/β-catenin/TCF4 signaling specifically in liver cancer cells by physically binding to β-TrCP, COP1, and SMAD ubiquitination regulatory factor 1 (SMURF1)." (PMID 37686524, 2023). "Given that TRIB2 is an antioxidant in liver cancer cells, TRIB2 might be an ideal target for the treatment of liver cancer." (PMID 33414446, 2021). "Our data provide new evidence that further supports the supposition that the UPS is tightly regulated by TRIB2, and that blocking its function might be helpful in the treatment of liver cancer by increasing oxidative damage." (PMID 33414446, 2021). "Together, βTrCP is required for TRIB2 to modulate the ubiquitination of TFRC in liver cancer cells." (PMID 34315867, 2021). "Tribbles homolog 2 (TRIB2) is known to affect Ub E3 ligases (E3s) in liver cancer." (PMID 33414446, 2021). "TRIB2 has the capacity to reduce global Ub; however, TRIB2 is upregulated in liver cancer cells." (PMID 34315867, 2021). "Then, we assessed whether TFRC and βTrCP contribute to the effects by which TRIB2 desensitizes liver cancer cells to ferroptosis that induced by RSL3 and erastin." (PMID 34315867, 2021). "Appropriate reduction of TRIB2 function might be beneficial for patients bearing liver cancer because it will definitely sensitize ferroptosis-based therapy." (PMID 34315867, 2021). "Next, we investigated how TRIB2 reduces labile iron in liver cancer cells." (PMID 34315867, 2021). "In addition, all of these effects were reversed by treatment with PCBP2, suggesting that PCBP2 and TRIB2 increase liver cancer cell viability." (PMID 33414446, 2021). "In our previous works, we noticed that TRIB2 exerts a similar function in liver cancer cells." (PMID 33414446, 2021). "The specific effects of TRIB2 knockdown were further proven by the prevention of simultaneous TRIB2 overexpression, indicating that TRIB2 might negatively regulate Ub levels in liver cancer cells." (PMID 33414446, 2021). "Collectively, these results demonstrated that TRIB2 desensitizes liver cancer cells to ferroptosis." (PMID 34315867, 2021). "However, in terms of feedback regulation, TRIB2 stability has also been shown to be regulated at the protein level in liver cancer cells, in part due to the downregulation of the E3 ligase SMURF1." (PMID 27908682, 2017). "We have previously shown that TRIB2 inhibition either through TRIB2 knockdown or via inhibition of an E2F1-TRIB2 regulatory loop results in perturbation of the cell cycle and cell death, and TRIB2 level was shown to be under the control of the β-TRCP ubiquitin E3 ligase in liver cancer cells." (PMID 27563873, 2016). "Finally, we investigated whether TRIB2 exclusively regulates ferroptotic cell death in liver cancer cells." (PMID 34315867, 2021). "However, the role of TRIB2 in human liver cancer cells is not completely known." (PMID 33414446, 2021). "The O-GlcNAcylation of TRIB2 induced by the HBP increased its protein stability, which in turn promoted transformative characteristics in liver cancer cells." (PMID 39199296, 2024). "TRIB2 regulated the β-TrCP-induced ubiquitination of TFRC, resulting in ferroptosis desensitization in liver cancer cells." (PMID 39199296, 2024). "One study revealed that TRIB2 is a downstream target of the Wnt pathway and regulates YAP and C/EBPα in liver cancer cells." (PMID 39199296, 2024).